SLC7A13 (solute carrier family 7 member 13)
Description:
Associates with SLC3A1/rBAT to form a functional heterodimeric complex that transports anionic and neutral amino acids across the apical plasma membrane of renal epithelium. Preferentially mediates exchange transport, but can also operate via facilitated diffusion. May act as a major transporter for L-cystine in late proximal tubules, ensuring its reabsorption from the luminal fluid in exchange for cytosolic L-glutamate or L-aspartate.
Synonyms: AGT1; XAT2; AGT-1
Tractability: Antibody: UniProt places it where antibodies can reach, with medium confidence; UniProt predicts a signal peptide or a membrane-spanning region; its Gene Ontology location is reachable by antibodies, with medium confidence.
Gene: Protein-coding gene on chromosome 8 (86,214,063 to 86,321,146, reverse strand). Ensembl gene ENSG00000164893.
Subcellular location: Apical cell membrane
Gene Ontology:
Molecular function: L-amino acid transmembrane transporter activity; transmembrane transporter activity
Biological process: amino acid transmembrane transport; aspartate transmembrane transport; L-alpha-amino acid transmembrane transport; L-cystine transport; L-glutamate transmembrane transport; transmembrane transport
Cellular component: apical plasma membrane; plasma membrane; membrane
Genetic constraint (gnomAD): Loss-of-function variants: 32 observed, 33.76 expected, observed/expected ratio (o/e) 0.95, 90% interval 0.71 to 1.27. The upper end of that interval is the gene's LOEUF score, 1.27, which puts it in group 5 of 6, group 1 being the genes least tolerant of losing a copy. Missense variants: 622 observed, 562.64 expected, observed/expected ratio (o/e) 1.11, 90% interval 1.03 to 1.18. Synonymous variants: 229 observed, 213.29 expected, observed/expected ratio (o/e) 1.07, 90% interval 0.96 to 1.2.
Homologues: Orthologues: chimpanzee SLC7A13 (99% identical), macaque SLC7A13 (97% identical), rabbit SLC7A13 (73% identical), mouse Slc7a13 (70% identical), rat Slc7a13 (70% identical), guinea pig SLC7A13 (67% identical), pig SLC7A13 (60% identical), Drosophila melanogaster mnd (33% identical), zebrafish si:ch73-352p4.8 (30% identical), Caenorhabditis elegans aat-1 (30% identical), Drosophila melanogaster CG1607 (30% identical), Caenorhabditis elegans aat-2 (29% identical), and 16 more. Paralogues in human: SLC7A6 (33% identical), SLC7A9 (31% identical), SLC7A7 (31% identical), SLC7A8 (30% identical), SLC7A10 (30% identical), SLC7A11 (29% identical), SLC7A5 (29% identical), SLC7A2 (21% identical), SLC7A1 (21% identical), SLC7A14 (21% identical), SLC7A3 (21% identical), SLC7A4 (20% identical).
Diseases named in the same sentence as SLC7A13 in open-access papers:
SLC7A13 is named in the same sentence as 3 diseases in open-access papers, as found by Europe PMC text mining. Sharing a sentence is not in itself a finding about the gene and the disease. The quoted sentences say what the papers report.
cystinuria (4 papers, 2018 to 2025). Cystinuria is a renal tubular amino acid transport disorder characterized by recurrent formation of kidneys cystine stones. "Additional research in different cohorts of cystinuria patients is essential to find rare, pathogenic, homozygous variants in SLC7A13 to fully characterize its impact on cystinuria." (PMID 38138969, 2023). "After characterizing the transport function of the four missense SLC7A13 variants, the effect of c.745G>A (p.V249M) and c.988C>T (p.L330F) variants on aspartate, glutamate, and cystine excretion in cystinuria patients was analyzed." (PMID 38138969, 2023). "Subsequent screening of the SLC7A13 gene in these patients revealed only benign polymorphisms, leading to the exclusion of SLC7A13 as the third causative gene for cystinuria in their cohort." (PMID 38138969, 2023). "The recently described novel cystine transporter SLC7A13/AGT1 in the renal proximal tubule was a promising candidate to harbor pathogenic mutations in cystinuria patients." (PMID 30342472, 2018). "Moreover, despite being the second renal cystine transporter identified, the impact of SLC7A13 variants in cystinuria has only been addressed in 17 genetically uncharacterized patients, and its potential modulatory effect has yet to be assessed." (PMID 38138969, 2023). "We wondered whether the sex-dependent expression of Slc7a13 was the cause of the sex differences of Slc3a1 KO induced cystinuria, thus we generated Slc7a13 KO mice with CRISPR/Cas9 technology and crossed them with Slc3a1 KO mice to make a double KO (DKO) mouse." (PMID 40110490, 2025). "Consequently, AGT1/ SLC7A13 has been suggested as a further candidate gene for cystinuria, mutations in this factor might explain the so far unsolved cases of cystinuria in which mutations in SC3A1 and SLC7A9 had been excluded." (PMID 30342472, 2018). "In our study, SLC3A1, SLC7A9, and SLC7A13 genes were sequenced in 34 clinically diagnosed cystinuria patients." (PMID 38138969, 2023). "SLC7A13 is a membrane protein and serves as the second cystine transporter, which can enable the determination of the previously unidentified genetics of cystinuria." (PMID 36230932, 2022). "With the exclusion of SLC7A13/AGT1 as the third cystinuria gene, the question remains unanswered why analysis for the two cystinuria genes SLC3A1 and SLC7A9 succeeds only in up to 85%." (PMID 30342472, 2018). "Considering that the tested Slc7a13 and orchidectomy were not the underlying causes of sex differences in cystinuria, we conducted a bulk RNA sequencing on six Slc3a1 KO kidney samples (3 males and 3 females) to further investigate the underlying mechanism." (PMID 40110490, 2025). "Thus, we analyzed its function in mouse models of cystinuria, screened the SLC7A13 gene in 34 patients with different lithiasic phenotypes, and functionally characterized the identified variants." (PMID 38138969, 2023). "We here report on the results of our search for pathogenic genetic variants in SLC7A13 in a cohort of 17 patients without disease-causing variations in the known cystinuria genes." (PMID 30342472, 2018). "We screened a cohort of 17 cystinuria patients for SLC7A13 variants which were negative for SLC3A1 and SLC7A9 mutations." (PMID 30342472, 2018). "With the exclusion of SLC7A13/AGT1 as the third cystinuria gene accounting for the SLC3A1 and SLC7A9 mutation negative cases, it becomes obvious that other genetic factors should be responsible for the cystinuria phenotype in nearly 15% of patients." (PMID 30342472, 2018). "Despite strong evidences for an involvement of SLC7A13 mutations in cystinuria, we could not confirm a relevant role of SLC7A13 for the disease." (PMID 30342472, 2018). "Altogether, these data showed that even if the expression of Slc7a13 was higher in male kidneys, knocking out Slc7a13 cannot rescue the male severity of cystinuria, indicating that Slc7a13 did not have an impact on the sex difference of cystinuria." (PMID 40110490, 2025).
cystinuria (continued). "As no pathogenic variants were found in the SLC7A13 gene, they concluded that the novel cystine transporter AGT1/rBAT was not a third cystinuria gene." (PMID 38138969, 2023). "In addition, as patients with cystinuria mutations in the SLC3A1 gene have impaired the assembly of both cystine transporters, these patients were grouped without considering SLC7A13 variants." (PMID 38138969, 2023). "Despite these strong evidences, we could not confirm a relevant role of SLC7A13 as a third gene contributing to the pathology of cystinuria." (PMID 30342472, 2018).
breast carcinoma (2 papers, 2023 to 2026). "SLC7A13 amplification and overexpression were associated with worse overall survival and disease-free survival in patients with luminal breast cancer." (PMID 40916662, 2026). "SLC7A13: The SLC7A family has good diagnostic efficacy in breast cancer." (PMID 37468832, 2023). "Here, we report that the gene for SLC7A13, a member of the SLC7A13-SLC3A1 cystine transporter, was amplified and overexpressed in 19.7% and 49.7% of breast cancers, respectively." (PMID 40916662, 2026).
Malignant Brain Tumour (1 paper, 2013). "SNP41 and SNP137 are located in the coding regions of the solute carrier family 7 (anionic amino acid transporter), member 13 (SLC7A13) gene and Deleted in Malignant Brain Tumour (DMBT1) genes, respectively." (PMID 23691232, 2013).